INS (insulin)
Diseases named in the same sentence as INS in open-access papers (continued):
Sharing a sentence is not in itself a finding about the gene and the disease.
Glucose intolerance (continued). "The ability of PL to overcome β-cell quiescence and re-activate mitosis is mediated by the interaction of PL with prolactin receptors, since deletion of the prolactin receptor on β-cells abolished compensatory growth during pregnancy, leading to impaired insulin release and glucose intolerance." (PMID 28753672, 2017). "The excess of free fatty acids providesnegative feedback of the glycogen synthase, which can induce the peripheralresistance to insulin and glucose intolerance, in both muscle and liver which can explain the longitudinal relationship between HTWphenotype and glycemia identified in this study." (PMID 28562834, 2017). "Thus, CM seems to be an independent factor leading to prediabetes manifested by its contribution to glucose intolerance, reduced insulin sensitivity (i.e., HOMA-IR), and reduced DIOGTT." (PMID 28713332, 2017). "In our experiment, we observed that MSCs cocultured with insulin-resistant HepG2 cells could reduce inflammatory action and glucose intolerance; subsequent MSC-CM treatment further certified the anti-inflammatory effect of MSCs by their paracrine role." (PMID 29096724, 2017). "Naringin prevents PI-induced glucose intolerance and impairment of insulin signaling and as nutritional supplement it could therefore alleviate metabolic complications associated with antiretroviral therapy." (PMID 29121676, 2017). "Our results point to the opposite direction and suggest that BMT may lead to metabolic abnormalities, including reduced insulin secretion and glucose intolerance, which is specifically manifest on HFD." (PMID 28445487, 2017). "FIRKO mice displayed reduced insulin levels and resistance to age-related glucose intolerance." (PMID 28795262, 2017). "Finally, since rats fed a HFS showed glucose intolerance and high serum insulin concentration, a condition that stimulates lipogenesis, we studied the expression of genes involved in lipid metabolism in liver." (PMID 28680065, 2017). "The finding that diet seems to have a more direct influence on reduction in fasting insulin, than MVPA, could be biologically explained by the associations found in earlier studies between fiber and fat intake with glucose intolerance." (PMID 28606146, 2017). "Inhibition of class IA PI3K via knockout of pik3r1 and pik3r2 genes in mice led to a decrease in insulin secretion and increased glucose intolerance, suggesting that class IA PI3K in β-cells is important for maintaining intracellular Ca2+ levels and cell-cell synchronization." (PMID 28856166, 2017). "Moreover, high-fat diet (HFD)-fed Atf6α−/− mice displayed glucose intolerance, blunted insulin secretion, and reduced pancreatic insulin content due to β-cell failure." (PMID 28860159, 2017). "Furthermore, improvement on glucose intolerance and insulin sensitivity as well as amelioration of hepatic steatosis was also observed." (PMID 27176632, 2016). "Interestingly, troxerutin dramatically restored glucose intolerance and insulin signaling, and diminished hepatic gluconeogenesis in HFD-treated mice." (PMID 28029143, 2016). "To further describe the glucose intolerance and delayed insulin release observed in ILK cKO mice, we investigated whether the islet capillaries were perfused." (PMID 27995929, 2016). "Our study shows that compared to women with a normal OGTT, women with glucose intolerance had a similar insulin sensitivity but a lower beta-cell function postpartum, which remained significantly lower after adjustment of confounders such as age, BMI, ethnicity and breastfeeding." (PMID 27285104, 2016). "Compared to women with a normal OGTT postpartum, women with glucose intolerance postpartum had a similar insulin sensitivity but a lower beta-cell function, remaining significant after adjustment for confounders [ISSI-2 1.6 (1.2–2.1) vs. 1.9 (1.7–2.4),p = 0.002]." (PMID 27285104, 2016).
Glucose intolerance (continued). "Interestingly, WT→RIPK3−/− mice after 16 weeks of CD-HFD presented with a significantly stronger glucose intolerance and higher insulin levels than RIPK3−/−→WT animals." (PMID 27323669, 2016). "In addition, intracerebroventricular delivery of MetCCL5 interrupted hypothalamic insulin signaling and elicited peripheral insulin responsiveness and glucose intolerance." (PMID 27898058, 2016). "Importantly, islets from male βVps13cKO mice maintained on RC or on HFD responded normally with insulin secretion in response to either glucose or high KCl, consistent with mild, and late-onset, glucose intolerance in these animals." (PMID 27329800, 2016). "The correlation between chronic high intake of dietary fructose with increased energy intake, body weight, adiposity, hypertriglyceridemia, hyperlipidemia, hypertension, glucose intolerance and decreased insulin sensitivity in laboratory animal, all leading to MetS, is indisputable." (PMID 27708685, 2016). "Although aP2-CETPTg mice had increased insulin sensitivity, they displayed glucose intolerance and this could be due to beta cell dysfunction." (PMID 26973702, 2016). "Based on previous reports, we hypothesized that we would see glucose intolerance pre-transplant, and our patients in fact did have moderately lower insulin sensitivity compared to healthy controls." (PMID 27518102, 2016). "However, at the oldest age studied (over 30 months), the beta cell areas were decreased, insulin levels were reduced, and glucose intolerance was observed, indicating a failure of beta cell compensation (unpublished data)." (PMID 27441644, 2016). "The fact that MNK1-KO mice are nonetheless protected against glucose intolerance and insulin-insensitivity suggests that MNK1 may regulate peripheral insulin sensitivity." (PMID 27087055, 2016). "This may explain the mild glucose intolerance we observed, as intrahepatic triglyceride accumulation can impair insulin-induced suppression of hepatic glucose production." (PMID 27125896, 2016). "Furthermore, intraperitoneal GTT demonstrated increased glucose intolerance and higher plasma insulin levels in LFD-fed PHD−/− mice compared to their WT counterparts." (PMID 27094951, 2016). "Although naringin did not improve glucose intolerance, it was associated with reversal of weight loss, improved glycogen storage and insulin secretion in diabetic rats." (PMID 27073901, 2016). "Ghrelin inhibits insulin secretion in most animal studies, and blockade of pancreatic-derived ghrelin enhances insulin secretion and ameliorates the development of diet-induced glucose intolerance." (PMID 26042199, 2015). "The decrease of insulin clearance predicts the progression of glucose intolerance." (PMID 26623647, 2015). "The increased oxidative burden incurred by overexpression of SOD2 in the pancreas would be predicted to cause glucose intolerance independent of changes in muscle insulin action." (PMID 25992608, 2015). "In addition, both glucose intolerance and insulin secretion were significantly ameliorated, followed by improvement of malnutrition." (PMID 26233654, 2015). "Moreover, these EVs also induced diabetic phenotypes in mice, such as glucose intolerance after glucose administration and insulin injection." (PMID 26510393, 2015). "In mice fed the HFD for fifteen weeks, the administration of resin at 10 mg/kg significantly decreased the HFD-associated increase in body weight gain and net energy intake and alleviated glucose intolerance, as evidenced by decreases in plasma glucose and insulin levels." (PMID 25709707, 2015). "After six months, animals developed severe glucose intolerance with normal insulin levels." (PMID 25837985, 2015). "The glucose intolerance observed in adult SL rats indicates an imbalance between insulin production and action in these animals due to decreased insulin secretion from pancreatic island β cells and/or decreased insulin sensitivity in target organs." (PMID 26302954, 2015).
Glucose intolerance (continued). "SDT rats showed glucose intolerance accompanied with a defect in early phase insulin secretion." (PMID 26366137, 2015). "Glucose intolerance and insulin sensitivity were improved in LMP7−/− mice." (PMID 26515636, 2015). "Moreover, isolated P. panacis EVs induced typical diabetic phenotypes, such as glucose intolerance after glucose administration or systemic insulin injection." (PMID 26510393, 2015). "Variation in this biological pathway could result in abnormal insulin regulation and glucose intolerance, which are important phenotypes of PCOS." (PMID 26308735, 2015). "Glucose intolerance in the elderly may result from impaired insulin secretion, increased peripheral insulin resistance or changes in other hormone systems." (PMID 26623014, 2015). "Indeed, graft-removing nephrectomy completely abolished the plasma insulin and resulted in severe glucose intolerance." (PMID 25930156, 2015). "The progression of obesity to insulin resistance and to T2D involves the adaptive expansion of β-cells and increase of insulin secretion, and if this compensation is inadequate, glucose intolerance and T2D develop, with subsequent decline of pancreatic β-cell mass." (PMID 25923733, 2015). "Furthermore, the accumulation of β-amyloid induced glucose intolerance, although serum insulin levels were elevated during the late phase of oral glucose tolerance test (OGTT)." (PMID 25755673, 2015). "Cortisol decreases insulin sensitivity and adds to glucose intolerance at all hours of a day." (PMID 26257957, 2015). "However, supraphysiological levels of GCs (either exogenous or endogenous) induce adverse effects related to glucose homeostasis, such as decreased peripheral insulin sensitivity, glucose intolerance, and dyslipidemia." (PMID 25313308, 2014). "Furthermore, the identification of increased miR-184 expression can explain the simultaneous occurrence of both improved insulin sensitivity and glucose intolerance observed in mice on ketogenic diet." (PMID 24361012, 2014). "Moreover, prognosis is worse in HCC patients with glucose intolerance or increased fasting serum insulin level." (PMID 24586785, 2014). "However, rapamycin-treated HFD-fed mice showed increased glucose intolerance due to lower basal insulin levels, decreased expression levels of GLUT4 in the adipose tissue and, in the liver, decreased lipogenesis and increased gluconeogenesis." (PMID 24710396, 2014). "Similarly, adult rodents exposed to high doses of DDT had impaired insulin secretion, glucose intolerance, and elevated gluconeogenesis." (PMID 25076055, 2014). "Furthermore, the increase in fat mass is accompanied by a decrease in insulin sensitivity and glucose intolerance while circulating low density lipoprotein (LDL), triglycerides, fatty acids, and proinflammatory markers become elevated." (PMID 25400333, 2014). "We recently reported that the increase in hepatic Plin2 is twice that of mice fed a control-liquid diet and the upregulation of Plin2 temporally coincides with the onset of hepatic steatosis, glucose intolerance and increase in hepatic ceramides (lipids that can impair insulin signaling)." (PMID 24831094, 2014). "For example, the modulation of gut microbiota, e.g. dietary intervention with oligofructoses, reduced metabolic endotoxemia and the cecal content of LPS, improved glucose intolerance, insulin sensitivity and decreased body weight gain in both high-fat fed and ob/ob mice." (PMID 24410812, 2014). "Moreover, results of OGTT and ITT showed extreme glucose intolerance and insulin insensitivity in KKAy mice, demonstrating the significant systemic insulin resistance of diabetic KKAy mice." (PMID 24799887, 2014). "We performed the studies in model experiments in mice using the high-fat-fed insulin-resistant mice, which is a well-established model for glucose intolerance, and we used the recently developed technique to stimulate islet hormone secretion by mixed liquid meal gavage in mice." (PMID 23781322, 2013).
Glucose intolerance (continued). "Mice developing glucose intolerance, obesity, peripheral insulin resistance, hyperglycemia, hyperinsulinemia, and increased beta cell mass after a high fat diet feature decreased glucose-induced insulin secretion, Cx36 expression, and beta cell coupling." (PMID 24278783, 2013). "Glucose intolerance of GK rats is also thought to be partly due to impaired insulin sensitivity." (PMID 24106476, 2013). "Similarly to partial genetic HSL depletion, pharmacological HSL inhibition protects mice from insulin and glucose intolerance." (PMID 23431266, 2013). "According to Elahi and Muller and Stout, several glucose age-related responses occur, such as a decrease in glucose tolerance, inappropriate insulin secretion and insulin insensitivity occurs, where in turn, a number of possible mechanisms for glucose intolerance in the elderly exist." (PMID 24353564, 2013). "Furthermore, PRL-receptor deficient mice show an impaired development of pancreatic ß-cells, finally leading to a blunted insulin response and mild glucose intolerance." (PMID 23517652, 2013). "To evaluate a possible role in p-KO mice for the abnormal islet size distribution in reducing the in vivo insulin response and in glucose intolerance, we measured insulin secretion in batches of isolated islets of different sizes (>50 islets per mouse) in perifusion experiments." (PMID 23923060, 2013). "In the present study, glucose intolerance was present following rapid adipose tissue expansion and adipose tissue inflammation despite enhancement of lipid oxidation and maintenance of muscle insulin sensitivity." (PMID 23951235, 2013). "The consequent accumulation of incompletely oxidized substrates as well as increased mitochondrial stress may eventually result in impaired insulin function and glucose intolerance." (PMID 24339975, 2013). "Thus, glucose intolerance in HFD mice is likely due to a lower responsiveness of the liver to insulin which should translate to a slower lowering of blood glucose during an ITT." (PMID 23951235, 2013). "Skeletal muscle atrophy can impair cytokine and insulin signaling, which may result in glucose intolerance because more than 75% of glucose is handled by skeletal muscle." (PMID 24050662, 2013). "Therefore, our current study supports that the glucose intolerance and in vivo insulin secretion defect in pancreas-specific STAT3-KO mice is due to altered microvasculature in the pancreas, and not intrinsic beta-cell function." (PMID 23923060, 2013). "Therefore, mice fed KD for 6 days already exhibited impaired insulin sensitivity, resulting in glucose intolerance potentially." (PMID 23874946, 2013). "β cell-specific mice defective in XBP1 exhibit hyperglycemia and glucose intolerance due to decreased insulin secretion from their β cells, suggesting that XBP1 may be required for glucose-stimulated proinsulin processing and insulin secretion." (PMID 24705207, 2013). "However, arguably, the observations in lean rats especially, severe fat- loss and glucose -intolerance by 11β-HSD1 inhibition, caution us against extending this strategy to insulin resistant-normal (lean) individuals." (PMID 23284633, 2012). "However, after a certain period of extreme high-fat feeding, Cdkal1−/− mice come to gain fat, to show deterioration of insulin sensitivity, and eventually to exhibit apparent glucose intolerance." (PMID 23173044, 2012). "Glucose intolerance and insulin dysregulation are evident across a number of neurodegenerative diseases, may contribute to disease progression and are clearly worth ameliorating." (PMID 22384126, 2012). "Whether the unexpected low adiposity and normal insulin sensitivity despite the presence of glucose intolerance in the RenTgMK mice is secondary to hypoinsulinemia merits further investigation." (PMID 23308073, 2012).
Glucose intolerance (continued). "L-arginine deficiency could result delay in sexual maturity and development of sterility, impairment of the production of insulin, glucose intolerance, and impaired liver lipid metabolism and detoxification." (PMID 22623885, 2012). "Furthermore, exercise has shown to increase GLUT4 expression in human skeletal muscle approximately two to four times, leading to improvements in glucose intolerance and insulin action." (PMID 22988507, 2012). "To determine whether the glucose intolerance was due to islet-intrinsic or extrinsic factors, we measured fasting insulin levels and found mTR+/− mice with short telomeres had lower levels." (PMID 21423765, 2011). "However, maternal SE appeared to be an independent factor to determine glucose intolerance and some abnormal brain responses to insulin in offspring." (PMID 22076142, 2011). "Elevating insulin levels in blood after glucose challenge not only stimulates glucose transport into muscle and fat tissues but also suppresses hepatic glucose production and deregulation of either process can lead to glucose intolerance." (PMID 21195350, 2011). "Glucose intolerance with a concomitant decrease in insulin levels was seen between 28 days and up to 6 to 12 months and there can be a temporary increase of insulin levels shortly after the ligation, which is considered to be a side effect of acute pancreatitis." (PMID 22133269, 2011). "Interestingly, Sei1-null mice present lower number of islets, decreased β-cell area, impaired insulin secretion, and glucose intolerance." (PMID 20090907, 2010). "Hence, on one hand PDE3B KO mice are lean and have improved insulin secretion but they also exhibit glucose intolerance, insulin resistance and increased lipolysis." (PMID 19262749, 2009). "Strongly significant enhancement of fasting insulinemia and insulin secretion induced by HFD in 129S6, BALB/c and DBA/2 had little effect on glucose tolerance (BALB/c, DBA/2) or was associated with glucose intolerance (129S6), suggesting insulin resistance in these strains." (PMID 18301746, 2008). "Besides, glucose intolerance and insulin sensitivity were substantially impaired." (PMID 41384837, 2025). "Furthermore, PKDkd-EGFP expression protected mice from HFD-induced insulin and glucose intolerance." (PMID 41349796, 2025). "However, most phytocannabinoids appear to have the capacity to not only impact the kidneys through the SGLT2 receptor by inhibiting glucosuria but also have the potential to impact insulin secretion and insulin sensitivity, lower glucose intolerance, increase energy expenditure, and more." (PMID 40872492, 2025). "Mice lacking MafA display deficient insulin secretion and glucose intolerance postnatally." (PMID 41008194, 2025). "Furthermore, the lean refed mice continued to display mild glucose intolerance and reduced plasma insulin/c-peptide peaks compared with control mice during IVGTTs, even though their body weight, insulin sensitivity, and insulin secretion capacity had normalized." (PMID 40488531, 2025). "Furthermore, the increased blood glucose levels in the HFD animals align with the literature, which links HFD consumption to glucose intolerance and reduced insulin sensitivity, often resulting from adipose tissue inflammation and hepatic oxidative damage as fat storage increases." (PMID 41374096, 2025). "Animals research has demonstrated that ketogenic diets can induce glucose intolerance, hepatic endoplasmic reticulum stress, steatosis, cell damage, and macrophage accumulation in mice, while not impairing insulin-induced Akt phosphorylation in the liver or systemic insulin reactivity." (PMID 39064712, 2024). "In mice, the shellfish-based western diet induced reduced glucose tolerance and insulin secretion compared to the diet based on lean fish, and we identified a number of metabolites elevated in plasma from shellfish-fed mice that correlated with glucose intolerance." (PMID 38637574, 2024).